SEC22A (SEC22 homolog A, vesicle trafficking protein)
Description:
May be involved in vesicle transport between the ER and the Golgi complex.
Synonyms: SEC22L2
Tractability: Antibody: UniProt predicts a signal peptide or a membrane-spanning region. PROTAC: ubiquitination databases record sites on it; its protein half-life has been measured.
Gene: Protein-coding gene on chromosome 3 (123,201,859 to 123,274,136, forward strand). Ensembl gene ENSG00000121542.
Subcellular location: Endoplasmic reticulum membrane
Subcellular location (Human Protein Atlas): Golgi apparatus; Vesicles
Pathways (Reactome):
Vesicle-mediated transport: COPII-mediated vesicle transport
Gene Ontology:
Molecular function: protein binding; SNAP receptor activity
Biological process: endoplasmic reticulum to Golgi vesicle-mediated transport; membrane fusion
Cellular component: endoplasmic reticulum membrane
Genetic constraint (gnomAD): Loss-of-function variants: 8 observed, 19.63 expected, observed/expected ratio (o/e) 0.41, 90% interval 0.24 to 0.74. The upper end of that interval is the gene's LOEUF score, 0.74, which puts it in group 3 of 6, group 1 being the genes least tolerant of losing a copy. Missense variants: 261 observed, 265.56 expected, observed/expected ratio (o/e) 0.98, 90% interval 0.89 to 1.09. Synonymous variants: 87 observed, 94.96 expected, observed/expected ratio (o/e) 0.92, 90% interval 0.77 to 1.1.
Homologues: Orthologues: chimpanzee SEC22A (100% identical), macaque SEC22A (99% identical), mouse Sec22a (97% identical), pig SEC22A (97% identical), guinea pig SEC22A (96% identical), dog SEC22A (96% identical), rat Sec22a (95% identical), zebrafish sec22a (70% identical), tropical clawed frog sec22a (69% identical), Drosophila melanogaster Syb (7% identical), Caenorhabditis elegans snb-2 (6% identical), Caenorhabditis elegans snb-5 (2% identical), and 2 more. Paralogues in human: SEC22C (40% identical), SEC22B (26% identical), YKT6 (9% identical), VAMP4 (8% identical), VAMP7 (8% identical), VAMP1 (7% identical), VAMP2 (6% identical), VAMP8 (5% identical), VAMP5 (5% identical), VAMP3 (4% identical).
Diseases named in the same sentence as SEC22A in open-access papers:
SEC22A is named in the same sentence as 1 disease in open-access papers, as found by Europe PMC text mining. Sharing a sentence is not in itself a finding about the gene and the disease.
SEC22A shares sentences with these, for which no sentence is quoted: infection (1 paper).